BICRAL (BICRA like chromatin remodeling complex associated protein)
Description:
Component of SWI/SNF chromatin remodeling subcomplex GBAF that carries out key enzymatic activities, changing chromatin structure by altering DNA-histone contacts within a nucleosome in an ATP-dependent manner.
Synonyms: GLTSCR1L; KIAA0240; SMARCK2
Tractability: No criterion of Open Targets' tractability assessment is met for any kind of drug.
Gene: Protein-coding gene on chromosome 6 (42,781,931 to 42,868,560, forward strand). Ensembl gene ENSG00000112624.
Subcellular location (Human Protein Atlas): Nucleoplasm; Cytosol
Pathways (Reactome):
Chromatin organization: Formation of the non-canonical BAF (ncBAF) complex
Gene Ontology:
Molecular function: protein binding
Biological process: chromatin remodeling; negative regulation of cell differentiation; positive regulation of cell population proliferation; positive regulation of DNA-templated transcription; positive regulation of stem cell population maintenance; regulation of transcription by RNA polymerase II
Cellular component: SWI/SNF complex; chromatin; GBAF complex; nucleoplasm
Genetic constraint (gnomAD): Loss-of-function variants: 3 observed, 61.03 expected, observed/expected ratio (o/e) 0.0492, 90% interval 0.021 to 0.13. The upper end of that interval is the gene's LOEUF score, 0.13, which puts it in group 1 of 6, group 1 being the genes least tolerant of losing a copy. Missense variants: 819 observed, 1,104.8 expected, observed/expected ratio (o/e) 0.74, 90% interval 0.7 to 0.79. Synonymous variants: 361 observed, 416.88 expected, observed/expected ratio (o/e) 0.87, 90% interval 0.79 to 0.94.
Homologues: Orthologues: chimpanzee BICRAL (99% identical), macaque BICRAL (99% identical), dog BICRAL (95% identical), pig BICRAL (92% identical), rat Bicral (88% identical), guinea pig BICRAL (88% identical), mouse Bicral (87% identical), rabbit BICRAL (85% identical), tropical clawed frog bicral (50% identical), zebrafish bicral (30% identical). Paralogues in human: BICRA (25% identical).
Diseases named in the same sentence as BICRAL in open-access papers:
BICRAL is named in the same sentence as 7 diseases in open-access papers, as found by Europe PMC text mining. Sharing a sentence is not in itself a finding about the gene and the disease. The quoted sentences say what the papers report.
Coffin-Siris Syndrome 3 (1 paper, 2023). "BICRAL is associated with Coffin-Siris Syndrome 3 in humans which causes congenital malformation and can cause feeding difficulties and poor growth." (PMID 37072725, 2023).
cancer (1 paper, 2023). A tumor composed of atypical neoplastic, often pleomorphic cells that invade other tissues. "Notably, genes encoding PBAF and ncBAF components such as PBRM1, ARID2, BICRAL (GLTSCR1L) and others were found to be more frequently mutated in cancer than in NDD." (PMID 37500730, 2023).
BICRAL also shares sentences with these, for which no sentence is quoted: glioma (1 paper); infection (1); myelodysplastic syndrome (1); prostate carcinoma (1); tumour (1).